NKIRAS2 (NFKB inhibitor interacting Ras like 2)
Description:
Atypical Ras-like protein that acts as a potent regulator of NF-kappa-B activity by preventing the degradation of NF-kappa-B inhibitor beta (NFKBIB) by most signals, explaining why NFKBIB is more resistant to degradation. May act by blocking phosphorylation of NFKBIB and nuclear localization of p65/RELA NF-kappa-B subunit. It is unclear whether it acts as a GTPase. Both GTP- and GDP-bound forms block phosphorylation of NFKBIB (By similarity).
Synonyms: KappaB-Ras2; KBRAS2; DKFZP434N1526
Tractability: PROTAC: ubiquitination databases record sites on it; its protein half-life has been measured.
Gene: Protein-coding gene on chromosome 17 (42,011,382 to 42,025,644, forward strand). Ensembl gene ENSG00000168256.
Subcellular location: Cytoplasm
Subcellular location (Human Protein Atlas): Nucleoli; Nucleoplasm
Pathways (Reactome):
Immune System: RIP-mediated NFkB activation via ZBP1; TAK1-dependent IKK and NF-kappa-B activation; TRAF6 mediated NF-kB activation
Gene Ontology:
Molecular function: protein binding; GTPase activating protein binding; GTPase activity; GTP binding
Biological process: negative regulation of canonical NF-kappaB signal transduction; Ral protein signal transduction
Cellular component: cytoplasm
Genetic constraint (gnomAD): Loss-of-function variants: 15 observed, 21.64 expected, observed/expected ratio (o/e) 0.69, 90% interval 0.46 to 1.07. The upper end of that interval is the gene's LOEUF score, 1.07, which puts it in group 4 of 6, group 1 being the genes least tolerant of losing a copy. Missense variants: 196 observed, 261.65 expected, observed/expected ratio (o/e) 0.75, 90% interval 0.67 to 0.84. Synonymous variants: 116 observed, 107.6 expected, observed/expected ratio (o/e) 1.08, 90% interval 0.93 to 1.26.
Homologues: Orthologues: chimpanzee NKIRAS2 (100% identical), dog NKIRAS2 (100% identical), macaque NKIRAS2 (100% identical), pig NKIRAS2 (100% identical), rabbit NKIRAS2 (100% identical), mouse Nkiras2 (99% identical), rat Nkiras2 (99% identical), guinea pig NKIRAS2 (97% identical), tropical clawed frog nkiras2 (81% identical), zebrafish nkiras2 (79% identical). Paralogues in human: NKIRAS1 (70% identical), RASD2 (29% identical), RALB (28% identical), HRAS (28% identical), RRAD (28% identical), RRAS (28% identical), KRAS (27% identical), NRAS (27% identical), RASD1 (27% identical), REM1 (26% identical), RRAS2 (26% identical), RALA (26% identical), and 23 more.
Diseases named in the same sentence as NKIRAS2 in open-access papers:
NKIRAS2 is named in the same sentence as 16 diseases in open-access papers, as found by Europe PMC text mining. Sharing a sentence is not in itself a finding about the gene and the disease. The quoted sentences say what the papers report.
glioblastoma (2 papers, 2020 to 2021). The most malignant astrocytic tumor (WHO grade IV). "Human miR-125b can regulate NKIRAS2 gene in periodontal ligament cells, glioblastomas, and MARC-145 cells." (PMID 34535180, 2021).
nasopharyngeal carcinoma (2 papers, 2020 to 2023). A carcinoma arising from the nasopharyngeal epithelium. "NKIRAS2 has been reported to mediate nasopharyngeal carcinoma cell growth and metastasis." (PMID 32950969, 2020). "NF- κB inhibitor interacting Ras-like 2(NKIRAS2), a negative regulator of the NF- κB signaling, was identified to be a direct target of miR-BART13 in nasopharyngeal carcinoma (NPC) cells, and promoted nasopharyngeal carcinoma cell growth." (PMID 37601252, 2023).
bladder cancer (1 paper, 2023). "In bladder cancer, we screened seven hub genes (ACLY, CNP, NKIRAS2, P3H4, PDIA6, VPS25 and XPO1) associated with survival." (PMID 37601252, 2023). "In addition, ACLY, NKIRAS2, XPO1 and tumor purity were significantly positively correlated (p < 0.001), which further indicates that ACLY, NKIRAS2 and XPO1 may be potential targets for the treatment of bladder cancer." (PMID 37601252, 2023).
breast carcinoma (1 paper, 2019). "It remains therefore unclear whether upregulation of NF-κB signaling aids to sensitize cells to Bortezomib or increases drug resistance in breast cancer and whether hsa-let-7a-5p increases Bortezomib sensitivity via downregulation of NKIRAS2 and TNFAIP3." (PMID 31063487, 2019).
renal carcinoma (1 paper, 2022). A carcinoma arising from the epithelium of the renal parenchyma or the renal pelvis. "The human protein atlas data shows that two out of three genes, i.e., NKIRAS2 (unfavorable) and AKTIP (favorable), are prognostic marker in renal cancer." (PMID 35039759, 2022).
skin papilloma (1 paper, 2021). A benign papillary neoplastic growth on the skin composed of epithelial cells and a fibrous stalk. "In the current study, we first found that K15 promoter-driven enforced expression of NKIRAS2 in follicle bulges exhibits potent tumor suppressive activity against the development of skin papilloma induced by treatment with DMBA and TPA." (PMID 34667224, 2021).
skin tumors (1 paper, 2021). "However, K15 promoter-driven expression of NKIRAS2 effectively suppressed the development of skin tumors induced by treatment with 7,12-dimethylbenz(a)anthracene (DMBA)/12-O-tetradecanoylphorbol 13-acetate (TPA)." (PMID 34667224, 2021).
urothelial carcinoma (1 paper, 2022). A malignant neoplasm derived from the transitional epithelium of the urinary tract (urinary bladder, ureter, urethra, or renal pelvis). "To test the prediction power of those genes, we developed a regression model for urothelial carcinoma that defined a set of 3 genes: NKIRAS2, AKTIP, and HLA-DQA1, which provides the likelihood of development of primary urothelial carcinoma with same estimation for male and female." (PMID 35039759, 2022).
cancer (2 papers, 2017 to 2021). A tumor composed of atypical neoplastic, often pleomorphic cells that invade other tissues. "Taken together, our results demonstrate that SRSF3 confers the malignant characteristics on cancer cells via the SRSF3/miR-1908-5p/NKIRAS2 axis." (PMID 28039456, 2017). "In conclusion, our results suggest that the SRSF3/miR-1908-5p/NKIRAS2 axis is closely associated with the oncogenic functions of SRSF3 and is a promising target for cancer treatment." (PMID 28039456, 2017). "Taken together, SRSF3 confers malignant phenotypes on cancer cells by upregulating the NF-κB-dependent miR-1908-5p expression and its oncogenic functions are enforced by positive feedback regulation of the NF-κB pathway via the SRSF3/miR-1908-5p/NKIRAS2 axis." (PMID 28039456, 2017).
tumor (2 papers, 2021 to 2023). "Therefore, we investigated whether the enforced expression of NKIRAS2 driven by the K15 promoter affected tumor formation caused by treatment with DMBA/TPA." (PMID 34667224, 2021). "On the other hand, only low numbers of tumors formed on DMBA-TPA-treated skin in both lines of NKIRAS2 transgenic mice, suggesting that K15 promoter-driven ectopic expression of NKIRAS2 suppressed DMBA/TPA-induced tumor formation." (PMID 34667224, 2021). "To investigate whether NKIRAS affects skin development and tumor formation, we generated transgenic mice forcibly expressing NKIRAS2 driven by the K15 gene promoter." (PMID 34667224, 2021). "In conclusion, NKIRAS2 seems to function as a tumor suppressor in follicle bulges." (PMID 34667224, 2021). "Moderate enforced expression of NKIRAS2 enhanced oncogenic RAS-provoked cellular transformation, whereas an excess amount of NKIRAS2 expression turned its functional direction to a tumor suppressive phenotype." (PMID 34667224, 2021).
infection (1 paper, 2021). The state of being infected such as from the introduction of a foreign agent such as serum, vaccine, antigenic substance or organism. "HRAS (G12V) was well expressed, and infection of NIH-3T3 cells with two kinds of retroviruses including sh-RNA against murine Nkiras2 caused effective reductions in Nkiras2 protein expression." (PMID 34667224, 2021).
NKIRAS2 also shares sentences with these, for which no sentence is quoted: bladder tumor (2 papers); Depression (1); hyperlipidemia (1); osteosarcoma (1); papilloma (1).